MTOR (mechanistic target of rapamycin kinase)
Diseases named in the same sentence as MTOR in open-access papers (continued):
Sharing a sentence is not in itself a finding about the gene and the disease.
cancer (continued). "Notably, the activation of the PI3K/AKT/mTOR pathway occurs in many types of cancer, and is one of the key downstream transduction signaling pathways of the IGF1R/IRS1 interaction." (PMID 33723215, 2021). "Interestingly, a number of strategies targeting mTOR and apoptotic priming concurrently have shown promise in improving anti-cancer therapeutic responses to tip the balance of BH3 signalling towards a pro-apoptotic phenotype." (PMID 34283054, 2021). "The PI3K/Akt/mTOR signal has always been considered as a crucial promoter of cell growth and cell cycle progression, which plays an essential role in the development and progression of cancers." (PMID 34572904, 2021). "The PI3K/AKT/mTOR pathway was a key link modulating the MDR of cancers." (PMID 34885972, 2021). "Further strategies in the development of anti-cancer compounds targeting ovarian malignancies include the suppression of proteins that affect the mTOR cascade, using siRNA, or the inactivation of AKT, PI3K, or simultaneous block of mTOR and PI3K, designing dual mTOR/PI3K inhibitors." (PMID 35582305, 2021). "Mechanistically, the longevity of the effects of combined HDAC and mTOR inhibition may be mediated through interference with MYC, as MYC-driven cancer cell lines seem to be particularly susceptible to this drug combination." (PMID 33658498, 2021). "Therefore, the PI3K/Akt/mTOR signaling pathway has become a focal point for cancer therapy and targeted drug development." (PMID 34408780, 2021). "In addition, mTOR, as the main negative regulator of autophagy in cancer cells, responds to specific signals between cell growth and autophagy, such as the nutritional status, growth factors, stress, and so on." (PMID 33494431, 2021). "In cancer, the mechanism of the mTOR pathway is more complicated." (PMID 34194607, 2021). "However, mTOR-targeted cancer therapies still face great challenges due to the anticancer efficacies of mTOR inhibitor monotherapy are limited in clinical treatment 24, 42-44." (PMID 33754064, 2021). "Besides, it has also been reported that mTOR plays a role in the development of drug resistance through a dependent or independent metabolism adaptation in cancer stem cells in response to chemotherapy or other stressors." (PMID 33828530, 2021). "Since PGE2/EP1/mTOR promoted YB-1 expression in other cancer cell types, we investigated whether PGE2/EP1 receptor and mTOR are also involved in the CD44v6 induced YB-1 expression in SW948-FR CICs." (PMID 33451103, 2021). "Everolimus inhibits mTOR proteins, which are multifunctional signal-transducing proteins that work downstream of different signaling pathways and affect protein translation in cancers." (PMID 33562829, 2021). "The PI3K/Akt/mTOR pathway is commonly deregulated in human cancer." (PMID 33946531, 2021). "Notably, we observed that key signaling proteins associated with mTOR and ERK-1/2 pathway including transforming growth factor-beta (TGF-β), Akt, and VEGFR showed racially disparate expression in cancer patients." (PMID 33996789, 2021). "AKT/mTOR signaling is involved in CSE1L-mediated cancer growth." (PMID 33854580, 2021). "The mTOR/HIF1α/ENO1 pathway can also enhance glycolysis in other cancers." (PMID 33968941, 2021). "Aberrant mTOR activation has been observed in many types of cancers including metastatic melanoma." (PMID 34304249, 2021). "PTEN, a tumor suppressor, is an antagonist regulator of the PI3K/AKT/mTOR signaling by inhibiting phosphorylation of PI3K, AKT, and mTOR, which was involved in the regulation of various cancers, including PCa, by participating in multiple tumor biological processes." (PMID 33648424, 2021).
cancer (continued). "More research to understand the molecular basis of mTOR networks and potential resistance mechanisms in mTOR-targeted cancer therapy are necessary to rationally apply mTOR inhibitors for the effective treatment of cancer." (PMID 33572326, 2021). "Several mTOR inhibitors have already undergone clinical trials for treating cancers." (PMID 33754064, 2021). "Accordingly, mTOR inhibitors have been intensively studied as potential anti-cancer agents." (PMID 33802831, 2021). "Although various methods have been tried to overcome therapeutic resistance in the different types of cancer, only two agents, mTOR inhibitor and CDK4/6 inhibitor, are currently available in the management of endocrine resistance, and there are still unmet therapeutic needs to improve outcomes." (PMID 34407787, 2021). "Moreover, GLRX3 was also reported to be involved in tumor initiation and progression in various types of cancers via NF-κB signaling, Notch signaling, stress-induced DNA damage responses, and mTOR signaling." (PMID 34794402, 2021). "Studies have suggested that AKT/mTOR inhibition suppresses the proliferation, migration, and survival of cancer cells while strengthening the immune surveillance of tumors by preventing immunosuppressive pathways from activating and enhancing the innate immunity against tumors." (PMID 33834064, 2021). "The PI3K/mTOR/AKT signaling pathway is dysregulated in various cancers." (PMID 34095461, 2021). "Several studies in cancer models suggest that Neurensin-2 regulates the PI3K/AKT/mTOR pathway in an unknown mechanism." (PMID 33723417, 2021). "Targeting mTOR signaling has generated significant interest for cancer therapy." (PMID 33946531, 2021). "Furthermore, the Hippo pathway has been implied to interact with multiple pathways including mTOR, Wnt, Hedgehog, and Notch, to regulate the proliferation of cancer cells." (PMID 34068565, 2021). "The mTOR pathway is important for growth development, and its signaling is involved in insulin signaling, growth factors, nutrition, energy metabolism, obesity, cancer, and other diseases." (PMID 33925400, 2021). "ANRIL interacts with signal transduction pathways in cancer such as PI3K/Akt/mTOR." (PMID 34072826, 2021). "mTOR is responsible for protein, lipid, and other synthesis pathways and is normally activated by the presence of growth factors or nutrients in the case of the placenta or is overactivated in cancer cells." (PMID 33916290, 2021). "Ras/Raf/MEK/ERK and PI3K/Akt/mTOR signaling pathways are responsible for regulating cell growth, proliferation, survival and apoptosis; and have been considered as promising targets for cancer therapy." (PMID 35069552, 2021). "Based on these findings, the PI3K/AKT/mTOR signaling pathway plays a pivotal role in cancer cell migration and invasion, and the blockade of molecules in this pathway represents a potential approach for cancer treatment." (PMID 34279440, 2021). "Therefore, it is extremely crucial to further explore the mTOR pathway when studying the pathogenesis of cancer." (PMID 34394184, 2021). "The PI3K/AKT/mTOR pathway is one of the most frequently dysregulated pathways in cancer and consequently, numerous compounds that target key components of this signaling pathway have been clinically tested in a range of different cancers." (PMID 33431926, 2021). "A logical target whereby metformin could mediate its putative antiproliferative effects in cancer is via inhibition of mTOR and the serine-threonine kinase, ribosomal S6K (pS6K), either via activation of AMPK or via an AMPK-independent pathway." (PMID 34421827, 2021). "In addition, TMPO-AS1 can accelerate cancer progression via activating AKT/mechanistic target of rapamycin kinase (mTOR) signaling." (PMID 34298879, 2021).
cancer (continued). "Previous studies indicated that the activation of AMPK/ULK1 pathway induced autophagy, and inactivation of the mTOR pathway could promote autophagy in multiple human cancers." (PMID 33898327, 2021). "A more detailed understanding of mTOR function and ways of partially inhibiting some of the mTOR-dependent processes, while maintaining others might therefore be the key to render mTOR a suitable cancer drug target." (PMID 34519269, 2021). "However, clinical data has shown that the effects of mTOR inhibitors utilized as single agents in cancer treatment are sometimes dampened by several resistance mechanisms." (PMID 33802643, 2021). "Similarly, BKM120 (0.25-1 μM) and BEZ235 (0-10 nM) enhance the radiosensitivity of cancer cells by targeting the PI3K-Akt/mTOR pathway." (PMID 36046754, 2021). "Previous observations highlight the significant role of mTOR signaling in mediating therapy resistance of cancer cells via entering a diapause-like dormant state depending on mTOR inhibition and autophagy activation, the same way as diapaused mESCs adapt and survive unfavorable conditions." (PMID 34832087, 2021). "Deregulation of the mTOR signaling pathway, including the loss of PTEN function, amplification/mutation of PI3K, and overexpression of S6K1, 4EBP1, eIF4E, and AKT, was described in multiple cancer types but mainly in melanoma." (PMID 34950252, 2021). "Accordingly, the inhibition of glycolysis/OXPHOS by DDM and RT treatment may result in cancer metabolic reprogramming via a novel PI3K/AKT/mTOR/P53NF-κB/VEGF pathway in BC cells." (PMID 34771733, 2021). "Interestingly, some upstream regulators have also been recognized in distinct cancer cells and silencing these activators have been shown to decrease L-Leu uptake and subsequent mTOR activity and proliferation of cancer cells." (PMID 35011270, 2021). "Notably, PTEN has been reported to be frequently mutated in human cancers and is a well‐known anti‐oncogene that encodes a dual‐specificity phosphatase antagonizing the phosphatidylinositol 3‐kinase (PI3K) class I/AKT/mTOR pathway." (PMID 33332708, 2021). "The mTOR signaling pathway has been reported to be overactivated in more than 70% of cancers." (PMID 34194607, 2021). "It is known that the transport of amino acids by LAT1 in cancer cells could activate the mTOR pathway." (PMID 34681614, 2021). "As well, AKT-AMPKα-mTOR signaling is a promising target for cancer therapy." (PMID 35095479, 2021). "In this mini review, we discuss a symbiotic relationship between the clocks and cancer as well as its relation with cancer-related metabolic pathways such as IGF-1R/mTOR/Akt signaling that could drive tumorigenesis." (PMID 33672910, 2021). "The results suggested that cancer- and immune-related ‘Hallmark’ gene sets, such as epithelial-mesenchymal transition, inflammatory response, PI3K/AKT/mTOR signaling pathway, and Wnt/β-catenin signaling pathway that were highly enriched in the high−risk phenotype." (PMID 34568046, 2021). "WB demonstrated the ratio of p-mTOR to mTOR was higher in ccRCC than adjacent specimens (n = 3), and IHC analysis elucidated that p-mTOR expression was positively correlated with tumor size, stage and metastasis status, and negatively correlated with cancer-specific survival (CSS)." (PMID 34458019, 2021). "We conclude that MAPK6 can promote cancer by activating AKT independent of mTORC2 and targeting MAPK6, either alone or in combination with mTOR blockade, may be effective in cancers." (PMID 34767444, 2021). "Moreover, a simultaneous use of MM-129 with 5-FU enhances the sensitivity of cancer cells through Akt, mTOR, and CDK2 inhibition." (PMID 34206937, 2021). "Since earlier findings reported that inhibition of mTOR pathway is leading to enrichment of cancer stem cells, high DDIT4 expression could be related to expression of stem-cells markers." (PMID 34107956, 2021).
cancer (continued). "Contrarily, suppression of mTOR effectively inhibits tumor growth and prolongs survival in cancers." (PMID 34016142, 2021). "Glycolysis regulating factors, such as hypoxia-inducible factor-1 (HIF-1), phosphoinositide 3-kinase/protein kinase B/mammalian target of rapamycin (PI3K/Akt/ mTOR), involve the switch of the glycolytic pathway, contributing to cancer proliferation and metastasis." (PMID 34717757, 2021). "Furthermore, quercetin promotes protective autophagy in cancer cells by forming autophagic vacuoles and acidic vesicular organelles (AVOs), activating autophagic gens, and inhibiting Akt-mTOR signaling and stabilizing HIF-α expression." (PMID 33746748, 2021). "Since the Akt/mTOR signaling pathway is often found to be highly active in cancer cells, this could be a potential route of therapy for cancer." (PMID 34065929, 2021). "Inhibition of mTOR C1 reduces glycolysis of cancer cells.EMT can promote tumor cell infiltration and tumor metastasis and may also make tumor cells escape apoptosis induced by some factors." (PMID 33546693, 2021). "The AKT/mTOR pathway is known to facilitate cell proliferation and survival in various cancers." (PMID 33390784, 2021). "As preclinical studies have shown, leucine supplementation could be a co-adjuvant therapy as it effectively maintains the mTOR pathway in animal models, minimising some damage effects in the placenta and foetus in the context of cancer." (PMID 33916290, 2021). "Therefore, the combination of inhibitors that hit more than one kinase in the PI3K/AKT/mTOR phosphorylation cascade appears as a promising therapeutic alternative against different types of cancer." (PMID 33477701, 2021). "The PI3K/Akt/mTOR pathway is frequently activated in human cancers." (PMID 33959611, 2021). "Interestingly, the phosphoinositide 3‐kinase (PI3K)/AKT/mTOR signal pathway, one of the most commonly deregulated pathways in human cancers, has been verified to be modulated by PDK1 and VEGFA." (PMID 34431227, 2021). "At the center of a complex regulatory network, the NRF2/KEAP1 pathway is emerging as a critical regulator of metabolism in cancer cells as its interactions with the metabolism-related pathway including the PI3K/AKT/mTOR pathway, p62 pathway, AMPK, and TCA cycle have been revealed." (PMID 33922165, 2021). "In other neoplasms, the specific inhibition of more than one PI3K isoform, as well as the dual inhibition of PI3K and mTOR, can increase the efficacy by affecting the survival of cancer cells both directly and through the action mediated by the microenvironment." (PMID 34638901, 2021). "Inhibition of PI3K/mTOR signalling pathway in cancers is also very important source of ER (endoplasmic reticulum) stress and subsequent UPR (unfolded protein response) activation, thanks to which cancer cells survive under severe physiological and cellular conditions." (PMID 34768941, 2021). "In conclusion, mTOR inhibition has enormous potential in clinical cancer therapy." (PMID 34916492, 2021). "A2M mutation was related to inflammatory cascades and might facilitate cancer development by decreasing the expression of CD29 and CD44, in addition, T790M, mTOR mutation and KEAP1 loss were identified as resistance mechanisms." (PMID 33740125, 2021). "Furthermore, TQ suppressed the PI3K/Akt pathway and inhibited the phosphorylation of Akt and mTOR, hence inhibiting cancer progression." (PMID 33923474, 2021). "mTOR also acts as a downstream of AKT to regulate cancer cell apoptosis." (PMID 34755451, 2021). "In addition, mTOR plays an important role in cancer therapies because it participates in cell growth, proliferation, autophagy and survival." (PMID 33413302, 2021). "In this review, we summarize the role of the circadian clock in regulation of one important metabolic pathway, insulin/IGF1/PI3K/mTOR signaling, and how dysregulation of this metabolic pathway could lead to uncontrolled cancer cell proliferation and growth." (PMID 33672910, 2021).
cancer (continued). "This research provides more evidence of the important role of mTOR in WH and cancer being a key target for therapy, whether promoting tissue regeneration or by preventing cancer growth when blocked." (PMID 34446793, 2021). "Dysregulation of the mTOR pathway disturbs the homeostasis of cells that may help in the metastasis of cancers." (PMID 33996789, 2021). "However, the clinical results of the first‐generation mTOR inhibitor rapamycin and its derivatives in the treatment of most types of cancer have been disappointing." (PMID 33507584, 2021). "We could suggest that inhibition of mTOR activity by ethyl ferulate exerts multiple effects on tumor progression, cancer growth, and cell cycle by modulating the mTOR signaling pathway." (PMID 35155187, 2021). "PI3K-AKT is one of the most important signaling pathways, which is differentially activated among different races and may modulate the mTOR pathway in several human cancers." (PMID 33996789, 2021). "Also, baicalein can inhibit MAPK, Akt, or mTOR to hold up the abnormal proliferation of cancer cells." (PMID 33688358, 2021). "mTOR could be a key factor in the development and progression of many conditions (such as metabolic diseases, obesity, cancer, and ageing)." (PMID 34444753, 2021). "Thus, targeting the PI3K/Akt/mTOR signaling pathway would be an attractive potential therapeutic target in cancer." (PMID 35250965, 2021). "In addition, amplification of the phosphatidylinositol 3-kinase (PI3K)/Akt/mammalian target of rapamycin (mTOR) signaling cascade is frequent in HPV-induced cancers." (PMID 34666780, 2021). "Ours and others’ findings on the role of therapy-induced selective autophagy in cancer progression suggest that a novel strategy could be to target mitochondrial functions and mTOR pathways simultaneously." (PMID 34360785, 2021). "This is supported by the latest data indicating that blastocysts that are naturally suspended in diapause in vivo and paused blastocysts ex vivo demonstrate a pronounced reduction in mTOR activity and an increase in autophagy activation in a similar manner with dormant cancer cells." (PMID 34832087, 2021). "Our results provide credible evidence that treatment with UF extract and UDCA could prevent cancer cell growth, proliferation, survival, and invasion by regulating the Akt/mTOR signaling pathway." (PMID 34500742, 2021). "However, no relevant clinical trials have been conducted until now, thus early stage clinical studies are needed to understand the feasibility and efficacy of these dual PI3K/mTOR inhibitors in combination with radiotherapy in cancer patients." (PMID 33790792, 2021). "The AKT/mTOR signaling pathway is frequently activated in a wide variety of cancers." (PMID 34512155, 2021). "Moreover, mTOR is a drug target related to the development of cancer, and its inhibitors are usually used for the eradication of cancer and tumor stem cells." (PMID 34527062, 2021). "Numerous studies have shown the importance of the mTOR pathway in cancer pathogenesis." (PMID 34356619, 2021). "We discovered that several of the miRs might act as a network regulating essential (CRC) cancer-associated pathways, e.g., the EGFR, MAPK, Ras, or the mTOR signaling pathway, amongst others." (PMID 34885060, 2021). "The PI3K/AKT/mTOR is a common example of a hyper-activated signaling pathway in cancer cells." (PMID 33946916, 2021). "And it is an essential component of a rapamycin-insensitive mTOR complex in cancers." (PMID 34926692, 2021). "Besides that, the tumor cell lines SCC25 and Detroit 562 represent genetic changes encountered in EGFR/RAS/RAF/MEK/ERK and EGFR/PI3K/AKT/mTOR signaling that play a pivotal role in cancer development and resistance." (PMID 33718274, 2021). "Mammalian target of rapamycin (mTOR)-controlled autophagy is also affected by intracellular Ca2+ levels and might support cancer cell survival strategies." (PMID 34298770, 2021).